SALL4 (spalt like transcription factor 4)
Diseases named in the same sentence as SALL4 in open-access papers (continued):
Sharing a sentence is not in itself a finding about the gene and the disease.
Intellectual disability (1 paper, 2025). "In the rare cases of intellectual disability reported, such phenotypes were attributed to broader deletions on chromosome 20q13.13-q13.2 rather than SALL4 loss alone." (PMID 41312722, 2025).
IVIC syndrome (1 paper, 2023). IVIC syndrome is a very rare genetic malformation syndrome characterized by upper limb anomalies (radial ray defects, carpal bone fusion), extraocular motor disturbances, and congenital bilateral non-progressive mixed hearing loss. "SALL4 mutations cause extremely variable conditions including Duane-radial ray (DRR), Okihiro, Holt-oram, Acro-renal ocular and IVIC syndromes, all with autosomal dominant inheritance pattern." (PMID 36829172, 2023). "IVIC syndrome was first identified in 1980 through allelic heterogeneity in the SALL4 gene of six generations of a Venezuelan family with autosomal dominant pleiotropic traits." (PMID 36829172, 2023).
keloid (1 paper, 2025). An irregularly shaped, elevated mark on the skin caused by deposits of excessive amounts of collagen during wound healing. "USP37 promotes keloid pathogenesis by stabilizing SALL4 through deubiquitination, thereby sustaining PI3K/AKT activation and driving fibroblast growth, migration, invasion, glycolysis, and ECM accumulation." (PMID 41424791, 2025). "Inhibition of USP37 or PI3K/AKT signaling attenuates these effects, highlighting the USP37/SALL4 axis as a critical regulator of keloid progression." (PMID 41424791, 2025).
large cell carcinoma (1 paper, 2016). A malignant epithelial neoplasm composed of large, atypical cells. "ADC cell line H522 and large cell carcinoma (LCC) cell line H661 showed the highest SALL4 RNA expression level among the 16 cell lines, which was confirmed by immunoblotting at protein expression level." (PMID 27705911, 2016).
liver disease (1 paper, 2025). "This contradicts previous assumptions that ductular reaction positively correlates with liver disease severity, suggesting that SALL4 in HCs may regulate ductal proliferation via a paracrine mechanism during the injury." (PMID 40932240, 2025). "This could help determine how SALL4 functions in HCs and/or CCs in liver disease." (PMID 40932240, 2025).
lymphoepithelioma-like carcinoma (1 paper, 2021). "In addition, another GC subtype, lymphoepithelioma-like carcinoma (LELC) of GC, featured with intense lymphocytic infiltration and partially overlapped with EBVaGC subtype, was SALL4-negative." (PMID 33644042, 2021).
mediastinal tumors (1 paper, 2014). "In addition, our data also suggests that NSCLC should be added to the differential diagnosis of SALL4/OCT4 positive neoplasms, particularly in patients with mediastinal tumors." (PMID 25346886, 2014).
mole (1 paper, 2021). "The immunostaining digital quantitative assessment visually confirmed SALL4 overexpression in postmolar choriocarcinoma compared to that of complete mole samples." (PMID 34680590, 2021). "SALL4 was expressed in the cytotrophoblast of most postmolar choriocarcinoma samples, with heterogeneity among samples, while almost none of the complete mole samples showed SALL4 immunostaining." (PMID 34680590, 2021).
myeloproliferative neoplasm (1 paper, 2011). A clonal hematopoietic stem cell disorder, characterized by proliferation in the bone marrow of one or more of the myeloid (i.e., granulocytic, erythroid, megakaryocytic, and mast cell) lineages. "To evaluate long-term safety issues such as myeloproliferative neoplasm (MPN)-like features, we transduced SALL4 isoforms to mouse LSK cells and then performed syngeneic transplantations to allow for long-term follow-up." (PMID 21943195, 2011).
nasal polyp (1 paper, 2019). "In this study, we reported that SALL4 expression was strikingly upregulated in NPC tissues compared with noncancerous nasopharyngeal tissues (nasal polyp), and NPC patients in T3‐4 classification often showed higher expression of SALL4." (PMID 30907073, 2019).
neural tube defect (1 paper, 2024). A congenital defect characterized by failure of the neural tube to close completely; this results in the presence of openings in the brain or spinal cord. "Sall2 deficient mice may exhibit neural tube defect (NTD), depending on the genetic background, while compound deletion of Sall1, Sall2, and Sall4 led to more severe NTD, implying functional redundancy among Sal family members." (PMID 39349437, 2024).
odontogenic cyst (1 paper, 2022). A cyst in the jaw that arises from tissues of tooth development. "Chi-square test was applied to evaluate the association between SALL4 and fascin expression in odontogenic cysts and tumors." (PMID 38895097, 2022). "SALL4 expression in odontogenic cysts was strongly positive with greater than 75% cells exhibiting diffuse cytoplasmic staining." (PMID 38895097, 2022). "SALL4 expression in the cytoplasm of odontogenic cysts and tumors may represent inactive or mutant forms which requires further validation." (PMID 38895097, 2022). "In relation to odontogenic cysts, OKC and DC, the intensity of fascin was more than SALL4." (PMID 38895097, 2022). "Odontogenic tumors, AOT and developmental odontogenic cysts, COC (simple type) were negative for SALL4." (PMID 38895097, 2022).
odontogenic tumors (1 paper, 2022). "Regarding the evaluation of the statistical significance test, in all the odontogenic tumors, the staining intensity of fascin was similar compared to SALL4." (PMID 38895097, 2022).
ovarian clear cell adenocarcinoma (1 paper, 2024). A malignant glandular epithelial neoplasm characterized by the presence of clear and hobnail cells. "Furthermore, SALL4 is useful in distinguishing OYST from ovarian clear cell adenocarcinoma." (PMID 39309737, 2024).
ovarian clear cell cancer (1 paper, 2023). An invasive malignant neoplasm that arises from the ovary and is characterized by a predominance of clear and hobnail malignant epithelial cells. "SALL4, which originates in somatic tumors, may be useful in identifying YSTs and in the differential diagnosis of ovarian clear cell carcinoma." (PMID 37391759, 2023).
ovarian epithelial tumor (1 paper, 2012). A benign, borderline, or malignant tumor that originates from the surface epithelium of the ovary. "In this study, we showed that SALL4 expression in MMMTs was significantly higher compared to the reported incidence in other ovarian epithelial tumors." (PMID 22848863, 2012).
Phocomelia (1 paper, 2018). "Multiple observations suggest that identifying SALL4 as a substrate for the CUL4CRBN complex is an important step on the road to understanding how thalidomide triggers phocomelia." (PMID 30252647, 2018). "Taken together, these observations imply that partial degradation of SALL4, as accomplished by thalidomide, could be consistent with life, yet induce phocomelia." (PMID 30252647, 2018).
pineal germinoma (1 paper, 2023). "Immunohistochemical staining revealed high expression of glial fibrillary acidic protein, SALL-4 (sal-like protein 4), and placental-like alkaline phosphatase (PLAP) in the pineal tumor, which was confirmed to be a pineal germinoma." (PMID 38066820, 2023).
renal carcinoma (1 paper, 2017). A carcinoma arising from the epithelium of the renal parenchyma or the renal pelvis. "Out of the unique set of genes detected by BNNPT, a few were reported to be relevant to renal cancer or disease: CDCP1, GSTT1, E2F3, MAPK1, SALL4, SIRT1, ADAMTS13, Gfrα1, ASPH, MIR17HG, APOE, BMP4, RCOR1, NUMB and SEC63." (PMID 28986523, 2017).
sarcoidosis (1 paper, 2025). Sarcoidosis is a multisystemic disorder of unknown cause characterized by the formation of immune granulomas in involved organs. "Among the twelve common DEGs, SALL4, WNT10A, RASAL1, CAMK2B were significantly upregulated while GADD45B, KLF4, OLR1, CSF3, WIF1, RAMP3 and AGER downregulated in both sarcoidosis and LC as compared to the controls." (PMID 40797277, 2025).
serous adenocarcinoma (1 paper, 2012). An adenocarcinoma that is characterized by the presence of papillary patterns and cellular budding. "The positivity of SALL4 was usually detected in the epithelial components, which were usually high-grade serous adenocarcinoma." (PMID 22848863, 2012).
steatosis (1 paper, 2025). Increased lipid within the cytoplasm of cells. "Given that transient AKT-driven steatosis typically resolves as HCs undergo CCA fate conversion, these findings indicate that Sall4 overexpression interferes with HC-to-CCA fate switching by sustaining a progenitor-like, lipid-rich state." (PMID 40932240, 2025).
T cell lymphoma (1 paper, 2025). "To identify a tag that could efficiently knock down mouse PD-1, we connected various degron tags to the C-terminus of PD-1, including IKZF1/3, Sall4, ZFP91, and SD, and generated Jurkat human T cell lymphoma cell lines that stably expressed the mouse PD-1-degron tag." (PMID 40687785, 2025).
thoracic neoplasms (1 paper, 2024). "In the setting of thoracic neoplasms, it has been described that SMARCA4 loss correlates with poorer outcome and expression of SOX2, CD34, and SALL4, and SMARCB1 loss is mainly seen in thoracic neoplasms of a mesenchymal lineage." (PMID 39125735, 2024).
urothelial carcinoma (1 paper, 2022). A malignant neoplasm derived from the transitional epithelium of the urinary tract (urinary bladder, ureter, urethra, or renal pelvis). "There has also been a report of pure urothelial carcinoma with SALL4 positivity." (PMID 35027045, 2022).
ventricular septal defect (1 paper, 2018). The presence of a defect (opening) in the septum that separates the two ventricles of the heart. "Sequence screening for Chinese patients with SALL4-related syndromes (ventricular septal defects and POI) identified several distinct variants of SALL4 genes." (PMID 30388808, 2018).
tumor (190 papers, 2008 to 2026). "This unique expression pattern distinguishes it from other SALL4 isoforms, which are typically nuclear and associated with tumor aggressiveness in various cancers." (PMID 39905414, 2025). "SALL4 associates with the NuRD co-repressor complex to repress tumor-suppressor genes (e.g., Foxl1, Dusp4), which would otherwise inhibit proliferation and promote differentiation." (PMID 41373846, 2025). "SALL4, overexpressed in NR tumors, is associated with tumor progression and drug resistance, suggesting therapeutic potential." (PMID 38534332, 2024). "Another study found that SALL4-mediated upregulation of exosomal miR-146a-5p drives T-cell exhaustion by M2 tumor-associated macrophages in HCC." (PMID 38173713, 2023). "It has been discovered that the zinc finger protein encoded by SALL4 has diagnostic value as a transcription factor in a variety of solid tumors, which makes it a potential tumor marker for HCC." (PMID 36575044, 2022). "Our data demonstrated that high co-expression of SALL4/ALDH1A1 was found to be significantly associated with tumor aggressiveness and worse DSS or PFS in SOC patients." (PMID 35090523, 2022). "Cancer studies have investigated roles and functions of these two CSC markers separately in tumor progression, invasiveness and metastases so that high expression of SALL4 and low expression of ALDH1A1 are associated with advanced levels of the disease." (PMID 35090523, 2022). "The transcription factor, spalt like transcription factor 4 (SALL4), binds to the promoter of miR-146a-5p to directly control its expression in exosomes, thereby regulates the polarization of macrophages into M2 tumor-associated macrophages." (PMID 36428980, 2022). "For one thing, SALL4 is an underlying biomarker that activates signaling pathways and oncoproteins that promote tumor progression including Wnt/β-catenin, PI3K/AKT, Notch signaling pathway, and OXPHOS, as well as Bcl-2, TNF-α, and IFN-γ." (PMID 35216168, 2022). "In our series, the highest detected levels of mRNA transcripts in tumour tissue were those of the SALL4 gene, whose altered expression was associated with tumour size and adverse prognosis." (PMID 36077612, 2022). "In summary, SALL1 functions as a putative tumor suppressor in GBM, but SALL2 and SALL4 are crucial for tumor development and progression, which is associated with PI3K/AKT pathway activation and the maintenance of an undifferentiated aggressive phenotype." (PMID 34944911, 2021). "Mostly, the re-expression of SALL4 was associated with increased tumor cell proliferation and decreased patient survival." (PMID 34417458, 2021). "The co-expression of LINC-ROR and SALL4 was significantly associated with the depth of tumor invasion (T2; p = 0.002) and tumor grade of II (p = 0.05)." (PMID 33745265, 2021). "The clinical results of the SALL4-LINC-ROR association propose a probable functional interaction between these markers in tumor maintenance and aggressiveness." (PMID 33745265, 2021). "Even though SALL4 has been reported to be strongly associated with tumor metastasis and promote migration and invasion in various cancers, its functional role in ccRCC metastasis remains elusive." (PMID 32513235, 2020). "Lastly, SALL4 is associated with drug resistance, which, in turn, hampers treatment of tumor cell growth." (PMID 32098783, 2020). "The overexpression of SALL4 has also been detected in patients with colorectal cancer, and its overexpression is associated with the grade of tumor cell differentiation and tumor cell metastasis to the lymph node." (PMID 29706061, 2018). "Collectively, these results suggested that knockdown of SALL4 enhances the sensitivity of EGFR mutation-positive tumor cells to Erlotinib in vivo." (PMID 29691367, 2018). "Furthermore, upregulation of the mRNA and protein of SALL4, Wnt3a, and β-catenin is associated with tumor differentiation in HCC." (PMID 35216168, 2022).
tumor (continued). "Moreover, we found that the co-expression of SALL4/ALDH1A1 proteins is associated with more aggressive tumor behavior, more advanced disease, and poor DSS, or PFS in SOC cases." (PMID 35090523, 2022). "EGFR mutated lung tumors expressed SALL4 to a significantly higher degree than non-tumor tissue." (PMID 34573282, 2021). "In addition to mechanistic studies in cell culture and in vivo models, we also examine clinical research studies showing diagnostic or prognostic correlates of microRNAs in tumor types in which SALL4 reactivation is known to play a pathogenic role." (PMID 34573282, 2021). "Unexpectedly, we found out that the reexpression of SALL4 in an adult testis is primarily associated with genome instability and mutations during tumor progression (invasion and metastasis) which may be important to explain DNA alterations found in TGCTs." (PMID 33224314, 2020). "Furthermore, the expression patterns of MEIS1 and stemness marker SALL4 were significantly associated to each other depending on different pathological features of the patients, specifically in early stages of tumor progression." (PMID 32819319, 2020). "The 20q13.3 gain herein reported is thus a novel anomaly associated to WT, suggesting that SALL4 might be relevant for the genesis of this tumor." (PMID 26317783, 2015). "Furthermore, higher levels of SALL4 mRNA expression were significantly associated with younger than older patients with tumor cells in stages I and II (P < 0.05)." (PMID 23363002, 2013). "SALL4 expression was significantly associated with tumor cell metastasis to lymph nodes (P < 0.05)." (PMID 23363002, 2013). "Expression analysis of SALL4 in normal and tumor colorectal tissues elucidated overexpression of SALL4 in a nearly 90% of CRC samples, where SALL4 expression was significantly associated with tumor cell metastasis to lymph nodes and the grade of tumor cell differentiation." (PMID 23363002, 2013). "Furthermore, IRS1 promotes the transcription of the tumor stem cell marker SALL4, suggesting that it might be implicated in the stemness property of CCA cells." (PMID 36768755, 2023). "Metastasis is a central problem during cancer therapeutics, as our result has indicated that the SALL4 expression was notably associated with lymph node metastasis, thereby we aimed to asses whether loss of SALL4 could affect tumor migration and invasion ability." (PMID 27329034, 2016). "Additionally, expression of SALL4 was associated with the grade of tumor cell differentiation." (PMID 23363002, 2013). "Due to insufficient prior tissue, a repeat core needle biopsy of the neck mass was pursued and suggested a poorly differentiated neoplasm with a germ cell phenotype, as IHC staining was SALL4-positive but CK AE1/3-negative." (PMID 40421964, 2025). "Distinguishing YST from other tumor types can be challenging; however, IHC markers, such as sal-like protein 4 (SALL4) and glypican-3 (GLP3), are useful for accurate identification." (PMID 40370888, 2025). "It is often observed that SALL4 is highly expressed in drug-resistant cell lines, and downregulating SALL4 can restore the chemotherapy sensitivity of tumor cells." (PMID 41340257, 2025). "For instance, the upregulation of WNT10A, RASAL1, CAMK2B, and SALL4 suggests their involvement in tumor-promoting processes, such as cell proliferation, migration, and immune evasion." (PMID 40797277, 2025). "The tumor was positive for spalt-like transcription factor 4 (SALL4) and GATA-binding protein 3 (GATA3), which established the diagnosis of PPC." (PMID 41625888, 2025). "METTL3 activates the Wnt/β-catenin signaling pathway by regulating the SALL4 target, promoting the renewal of tumor stem cells, leading to radiotherapy resistance in OSCC." (PMID 40823093, 2025). "To further elucidate the role of Sall4 in AY-CCA tumor formation, we investigated the effects of its gain-of-function in vivo." (PMID 40932240, 2025).